PDHA1 (pyruvate dehydrogenase E1 subunit alpha 1)
Diseases named in the same sentence as PDHA1 in open-access papers (continued):
Sharing a sentence is not in itself a finding about the gene and the disease.
lung adenocarcinoma (6 papers, 2022 to 2025). A carcinoma that arises from the lung and is characterized by the presence of malignant glandular epithelial cells. "Lung adenocarcinoma (LUAD) patients with high PDHA1 levels were significantly correlated with poor prognosis of overall survival (OS) and first progression (FP)." (PMID 36003495, 2022).
pyruvate dehydrogenase deficiency (6 papers, 2021 to 2024). A rare neurometabolic disorder characterized by a wide range of clinical signs with metabolic and neurological components of varying severity. "These included initiation of a ketogenic diet to patients with pyruvate dehydrogenase deficiency (mutations in PDHA1, PDHB, DLD), AGC1 deficiency (mutations in SLC25A12), and GLUT1 deficiency (mutations in SLC2A1)." (PMID 33726816, 2021). "PDHA1 (OMIM 300502) is an X‐chromosome gene, and PDHA1 mutation is the main reason for Pyruvate dehydrogenase complex deficiency (PDCD), and about 25% of PDCD can cause LS." (PMID 33661577, 2021). "The literature indicates that the c.506C>T variant has been found in three individuals with presentations aligning with PDHA1-related disease and it can be categorized as a pathogenic variant for PDHA1-related pyruvate dehydrogenase deficiency in an X-linked manner." (PMID 39720099, 2024).
glioma (5 papers, 2017 to 2023). A benign or malignant brain and spinal cord tumor that arises from glial cells (astrocytes, oligodendrocytes, ependymal cells). "In glioma patients, the levels of CDKN2A, FDX1, DLD, DLAT, LIAS, LIPT1, and PDHA1 were significantly associated with the OS, disease-specific survival, and progression-free interval." (PMID 36579333, 2022). "Further analysis of the relationship between CRGs and the prognosis of gliomas revealed that high expression of FDX1, DLD, DLAT, and LIPT1 was associated with poorer survival in glioma patients, and high expression of CDKN2A and PDHA1 was significantly associated with better survival in gliomas." (PMID 36915038, 2023). "It was reported that the increasing level of PDHA1 was observed in the higher grade of glioma and PDHA1 could regulate the migration of glioma cells." (PMID 36110851, 2022). "The expression of GLS (p < 0.001), LIPT1, FDX1, SLC31A1 (p < 0.01), DLST, CDKN2A, PDHA1, ATP7A, ATP7B, and NFE2L2 (p < 0.05) was different between glioma and adjacent tissues." (PMID 36936439, 2023). "For OS outcomes of glioma patients, a 9-gene signature was selected to construct the prognostic score using their regression coefficients: Riskscore = (0.8949)*FDX1 + (0.4902)*DLD + (0.0778)*DLAT + (-0.9324)*LIAS + (0.1132)*GLS + (0.903)*LIPT1 + (-0.1847)*MTF1 + (-0.2352)*PDHA1 + (-0.2045)*PDHB." (PMID 36915038, 2023).
colorectal cancer (4 papers, 2022 to 2025). A primary or metastatic malignant neoplasm that affects the colon or rectum. "RNF4-mediated ubiquitination of PDHA1 has been demonstrated to play a critical role in promoting glycolytic metabolism, proliferation, and metastasis in colorectal cancer, and PDHA1 overexpression has been shown to inhibit CRC cell proliferation, migration, and invasion." (PMID 41050056, 2025).
glioblastoma (4 papers, 2015 to 2022). The most malignant astrocytic tumor (WHO grade IV). "To test whether this dependence on extracellular lipids under PDH suppression could be extended to other rapidly proliferating cell lines, we used the same PDHA1 hairpins in SFXL glioblastoma cells." (PMID 26137220, 2015). "In contrast, PDHA1 was significantly downregulated in six tumors, namely, breast invasive carcinoma (BRCA), glioblastoma multiforme (GBM), kidney renal clear cell carcinoma (KIRC), kidney renal papillary cell carcinoma (KIRP), pheochromocytoma and paraganglioma (PCPG), and thyroid carcinoma (THCA)." (PMID 36003495, 2022).
neuropathy (4 papers, 2016 to 2024). A disorder affecting the nervous system that manifests with pain, tingling, numbness, and/or muscle weakness. "PDC-deficiency mainly caused by mutations in the PDHA1 gene in humans are rare, and is mostly manifested as severe neuropathies leading to death at very young age44." (PMID 28332581, 2017).
Ataxia (3 papers, 2016 to 2024). Ataxia refers to impaired coordination of voluntary muscle movement. "Although SURF1, SCO2 and some PDHA1-patients could be clinically well-defined, collection of such symptoms as median disease manifestation at 13 months, muscular hypotonia, hypertrichosis, ataxia and bilateral lesions in brainstem and/or basal ganglia are typical for the SURF1 gene cases." (PMID 36675121, 2023).
epilepsy (3 papers, 2019 to 2023). A brain disorder characterized by episodes of abnormally increased neuronal discharge resulting in transient episodes of sensory or motor neurological dysfunction, or psychic dysfunction. "PDHA1 mutations can produce disorders of mitochondrial function and have been implicated in disease states such as epilepsy and Alzheimer’s disease." (PMID 31010998, 2019).
esophageal squamous cell carcinoma (3 papers, 2022 to 2025). Esophageal squamous cell carcinoma (ESCC) is a type of esophageal carcinoma (EC) that can affect any part of the esophagus, but is usually located in the upper or middle third. "Its expression is higher in well-differentiated tumors, and low expression of PDHA1 is associated with poor prognosis in patients with esophageal squamous cell carcinoma." (PMID 36117848, 2022). "PDHA1 reduction drastically shifts the metabolism from oxidative phosphorylation to lactate production in cancers such as prostate and esophageal squamous cell carcinoma." (PMID 40090587, 2025).
microcephaly (3 papers, 2021 to 2024). A congenital or acquired developmental disorder in which the circumference of the head is smaller than normal for the person's age and sex. "Patients with pathogenic variants in the PDHA1 gene usually develop microcephaly postnatally; however, in the case of patient S89, lower OFC was observed at birth, and the abnormalities of the brain were more severe when compared to the other two patients." (PMID 34946966, 2021).
osteosarcoma (3 papers, 2023 to 2025). A usually aggressive malignant bone-forming mesenchymal neoplasm, predominantly affecting adolescents and young adults. "PDHA1 and CDKN2A were obtained as specific cuproptosis-related biomarkers for osteosarcoma after artificial intelligence analysis." (PMID 36967449, 2023).
ulcerative colitis (3 papers, 2022 to 2025). An inflammatory bowel disease involving the mucosal surface of the large intestine and rectum. "A study conducted on ulcerative colitis (UC) revealed that both LIPT1 and PDHA1 are key genes to promote cuproptosis, which can induce the abnormal death of intestinal epithelial cells and lead to the occurrence of UC." (PMID 40655146, 2025). "In ulcerative colitis, LIPT1 and PDHA1-related cuproptosis disrupts epithelial cells, advancing the disease." (PMID 40655146, 2025). "Cuproptosis-related regulators exhibited extensive differential expression in Crohn’s Disease (CD), Ulcerative Colitis (UC), Celiac Disease (CEL), and IBD-induced cancer (IBD-CA) that share common differential genes (PDHA1, DBT, DLAT, LIAS)." (PMID 36405733, 2022).
autism (2 papers, 2020 to 2024). Persistent deficits in social interaction and communication and interaction as well as a markedly restricted repertoire of activity and interest as well as repetitive patterns of behavior. "A mutation in the X-linked pyruvate dehydrogenase (PDH) alpha subunit gene (PDHA1) results in a deficiency of the majority PDH complex, which affects mitochondrial function and may contribute to brain dysfunction in autism." (PMID 37930872, 2024).
brain ischemia (2 papers, 2019 to 2024). Diminished or absent blood supply to the brain caused by obstruction (thrombosis or embolism) of an artery resulting in neurologic damage. "Our results indicated that SSS extraction decreased the expression of p-PDHA1 after cerebral ischemia, which contributed to the promotion of PDH activity." (PMID 31065240, 2019). "Eight hub genes (FDX1, LIPT1, LIAS, DLD, PDHA1, DLAT, PDHB, and GLS) were identified as potential core targets of cerebral ischemia." (PMID 39360273, 2024).
cardiomyopathy (2 papers, 2018 to 2025). A disease of the heart muscle or myocardium proper. "Interestingly, changes in FGF21-responsive genes such as OXCT1, the SUCL complex, PDHA1, OGDH, ACO2, IDH3B, and ETC components (MT-CO2, COQ9, UQCRQ, SDHB/D and NDUFB7) are linked to mitochondrial deficiency syndromes manifesting cardiomyopathy and encephalopathy." (PMID 40998786, 2025).
cervical cancer (2 papers, 2021 to 2025). A primary or metastatic malignant neoplasm involving the cervix. "Our results suggest the possible roles of CCDC22 and PDHA1 in the regulation of cuproptosis in cervical cancer, which deserves further investigation." (PMID 41142609, 2025). "Using this signature, the patients were divided into Cluster A and Cluster B. Compared with Cluster A, most cuproptosis genes (such as CCDC22, PDHA1, ARF1, and AQP1) in Cluster B were highly expressed, resulting in a better prognosis for patients with cervical cancer." (PMID 41142609, 2025). "Co-IP assays with an anti-STAT5A antibody demonstrated that endogenous STAT5A interacted with multiple PDC subunits, including PDHA1, PHDB, DLD, and DLAT in 293T, HeLa (a human cervical cancer cell line), MIHA (a human hepatocyte), and primary mouse hepatocytes." (PMID 34148062, 2021).
cervical squamous cell carcinoma (2 papers, 2022 to 2024). A squamous cell carcinoma arising from the cervical epithelium. "PDHA1 expression was significantly up-regulated in cervical squamous cell carcinoma (CSCC), cervical squamous cell carcinoma and endocervical adenocarcinoma (CESC), CCA, HCC, LUAD, LUSC, STAD, and UCEC." (PMID 39482784, 2024).
cognitive deficits (2 papers, 2021 to 2025). "In order to further explain the possible mechanism of cognitive impairment caused by the loss of PDHA1, we measured the lactate levels in the hippocampi of mice." (PMID 34720870, 2021). "Although there is substantial evidence that PDHA1 deficiency is closely related to neurodegenerative diseases and cognitive impairment, it is unclear whether the loss of PDHA1 in the hippocampus will harm cognitive function." (PMID 34720870, 2021). "In the future, we will include mice of different months in the study to explore the relationship between cognitive impairment and age in Pdha1–/– mice." (PMID 34720870, 2021). "In conclusion, our results suggest that Pdha1 knockout in the hippocampus leads to the accumulation of lactate and impairs gene expression behind learning and memory, resulting in memory and cognitive impairment." (PMID 34720870, 2021). "We hypothesized that lactate might be involved in cognitive impairment in Pdha1–/– mice through the cyclic AMP-protein kinase A-cAMP response element-binding protein (cAMP/PKA/CREB) signaling pathway." (PMID 34720870, 2021).
colon adenocarcinoma (2 papers, 2017 to 2022). "The total protein expression of PDHA1 was significantly decreased in colon adenocarcinoma (COAD), BRCA, KIRC, GBM, HNSC, and pancreatic adenocarcinoma (PAAD) and elevated in LIHC." (PMID 36003495, 2022). "We also looked at other genes involved in pyruvate transport and metabolism and interestingly, MPC1, MPC2, PDHA1 and PC showed consistent downregulation in a specific subset of colon adenocarcinomas known as colon mucinous adenocarcinomas (AC) (n = 22)." (PMID 28397687, 2017).
cyst (2 papers, 2015 to 2025). A sac-like closed membranous structure that may be empty or contain fluid or amorphous material. "Finally, we tested the effect of knocking down the gene encoding the α subunit of PdhE1, Pdha1, in cyst cells, hypothesizing that preventing mitochondrial consumption would increase the flux of pyruvate towards lactate production." (PMID 40777312, 2025). "Strikingly, Pdha1 knockdown in cyst cells resulted in significantly fewer Lysotracker-positive germ cell cysts compared to control testes, indicating that preventing autonomous pyruvate usage in cyst cells is beneficial for germ cell survival." (PMID 40777312, 2025).
diabetes (2 papers, 2021 to 2024). "In addition, our previous study found that the expression of PDHA1 protein is decreased significantly in the hippocampi of rats with diabetes-associated cognitive decline." (PMID 34720870, 2021). "The role of the constituent PDHA1 in diabetes is also being gradually elucidated." (PMID 38904034, 2024). "In conclusion, there is a growing recognition of the impact of PDC and its constituent components, DLAT, DLD, PDHA1, and PDHB, on diabetes." (PMID 38904034, 2024).
diffuse large B-cell lymphoma (2 papers, 2022 to 2025). "In AML, PDHA1 mRNA expression is typically reduced, whereas its expression is notably elevated in lymphoid neoplasms, including diffuse large B-cell lymphoma (DLBC) and thymoma (THYM)." (PMID 41357210, 2025). "We found the upregulated expression of PDHA1 in lymphoid neoplasm diffuse large B-cell lymphoma (DLBC) and thymoma (THYM) and the downregulated expression of PDHA1 in acute myeloid leukemia (LAML)." (PMID 36003495, 2022).
endometriosis (2 papers, 2023 to 2024). The growth of functional endometrial tissue in anatomic sites outside the uterine body. "Additionally, some copper metabolism-related genes, such as PDHA1, are downregulated during endometriosis, and mTOR is speculated to regulate copper metabolism in association with PDHA1." (PMID 39579091, 2024).
kidney cancer (2 papers, 2020 to 2022). Primary or metastatic malignant neoplasm involving the kidney. "Kidney cancer patient with SUCLG1, GLDC, SLC12A1, PCK2, ATP1A1 and PDHA1 alteration showed highest mortality." (PMID 32699530, 2020).
mucinous adenocarcinoma (2 papers, 2017 to 2022). An invasive adenocarcinoma composed of malignant glandular cells which contain intracytoplasmic mucin. "In tumors, we found that compared with adenocarcinoma, PDHA1 and GLS were expressed at low levels in mucinous adenocarcinoma, while CDKN2A was highly expressed." (PMID 36246586, 2022).
non-small cell lung carcinoma (2 papers, 2015 to 2025). A group of at least three distinct histological types of lung cancer, including non-small cell squamous cell carcinoma, adenocarcinoma, and large cell carcinoma. "PDH activity was suppressed in H460 non-small cell lung cancer cells using doxycycline-inducible shRNAs directed against the PDHA1 transcript." (PMID 26137220, 2015).
Obesity (2 papers, 2020 to 2023). Accumulation of substantial excess body fat. "To begin to assess the contribution of SHP2 and PDHA1 to adipocyte development, we first induced obesity in a cohort of mice using a high fat diet (HFD) and maintained a cohort of lean mice on regular chow diet." (PMID 36074246, 2023). "The high levels of p-SHP2 and PDHA1 in obese adipose tissues indicate important roles for SHP2 and PDHA1 in obesity initiation." (PMID 36074246, 2023). "Moreover, inhibition of SHP2, PDHA1, or ROS decreased the secretion of the pro-inflammation cytokine, IL-6, a key mediator of obesity-mediated PDAC hallmarks." (PMID 36074246, 2023).
pancreatic cancer (2 papers, 2021 to 2023). "In other cellular and biological contexts, adipocyte conditioned media (CM)-mediated induction of PDHA1 in pancreatic cancer cells appears to also be suppressed after SHP099 treatment." (PMID 36074246, 2023).
pulmonary fibrosis (2 papers, 2022 to 2023). Chronic progressive interstitial lung disorder characterized by the replacement of the lung tissue by connective tissue, leading to progressive dyspnea, respiratory failure, or right heart failure. "In the mouse model of pulmonary fibrosis induced by bleomycin, the genes related to cuproptosis promotion, such as Fdx1, Lias, Dld, Pdha1, Pdhb, Dlat, and Lipt1, were gradually down-regulated in the process of fibroblast differentiation from resting fibroblast to myofibroblast." (PMID 36601107, 2022). "It’s reported that the CRGs, such as FDX1, LIAS, DLD, PDHA1, PDHB, DLAT, and LIPT1, were down-regulated in the lung tissues of pulmonary fibrosis mouse model, and the same results were obtained via analysis of lung tissues scRNA-seq data for human pulmonary fibrosis." (PMID 37266442, 2023).
Pyruvate dehydrogenase complex deficiency (2 papers, 2021 to 2024). "Pathogenic variants in the PDHA1 gene cause pyruvate dehydrogenase E1-alpha deficiency (PDHAD; OMIM 31270) and are responsible for 76%–85% of primary pyruvate dehydrogenase complex deficiency cases." (PMID 39720099, 2024).
renal carcinoma (2 papers, 2020 to 2022). A carcinoma arising from the epithelium of the renal parenchyma or the renal pelvis. "Many studies have shown that SLC12A1, ATP1A1, and PDHA1 are low-expressed in renal cancer and play an important role in the development of tumors." (PMID 32699530, 2020). "It has been reported that Solute carrier family 12 member 1 (SLC12A1), Sodium/potassium-transporting ATPase subunit alpha-1 (ATP1A1) and Pyruvate dehydrogenase E1 component subunit alpha (PDHA1) are differentially expressed in renal cancer tissues." (PMID 32699530, 2020). "In this study, we analyzed the databases of GEO, TCGA, GEPIA, Oncomine, and found that six genes (SUCLG1, PCK2, GLDC, SLC12A1, ATP1A1, and PDHA1), are related to the survival prognosis of patients with renal cancer." (PMID 32699530, 2020).
sarcopenia (2 papers, 2023 to 2025). Progressive decline in muscle mass due to aging which results in decreased functional capacity of muscles. "According to the results of ROC analysis, PDHA1, DLAT, PDHB, and NDUFC1 were selected as the potential promising diagnostic biomarkers of sarcopenia." (PMID 37007946, 2023). "A total of four possible hub genes of sarcopenia were screened, namely, PDHA1, DLAT, PDHB, and NDUFC1." (PMID 37007946, 2023). "A total of four overlapping genes were extracted as the hub genes involved in sarcopenia and cuproptosis, which were PDHA1, DLAT, PDHB and NDUFC1." (PMID 37007946, 2023). "Our findings indicate the cuproptosis-related genes, PDHA1, DLAT, PDHB, and NDUFC1 are the diagnostic biomarker for sarcopenia, which provide evidence concerning the role of cuproptosis in sarcopenia." (PMID 37007946, 2023). "The four hub genes (PDHA1, DLAT, PDHB, and NDUFC1) were included to construct a diagnostic model for sarcopenia." (PMID 37007946, 2023). "The present study inferred the significance of mitochondrial dysfunction in the progression of sarcopenia, and the four cuproptosis-related genes, PDHA1, DLAT, PDHB, and NDUFC1, may serve as the potential targets for further therapeutic intervention." (PMID 37007946, 2023). "PDHA1 and PDHB were downregulated in sarcopenia patients, which indicated the dysfunction of mitochondrial respiration in sarcopenia patients." (PMID 37007946, 2023). "Intersection of DEGs, WGCNA and CRGs yielded four core genes (PDHA1, DLAT, PDHB, and NDUFC1) as potential biomarkers for the prediction of sarcopenia." (PMID 37007946, 2023).